SERPINI2 (serpin family I member 2)
Synonyms: MEPI; PI14; TSA2004; PANCPIN
Tractability: Antibody: UniProt places it where antibodies can reach, with high confidence; UniProt predicts a signal peptide or a membrane-spanning region; its Gene Ontology location is reachable by antibodies, with medium confidence.
Gene: Protein-coding gene on chromosome 3 (167,441,914 to 167,478,972, reverse strand). Ensembl gene ENSG00000114204.
Subcellular location: Secreted
Gene Ontology:
Molecular function: protein binding; serine-type endopeptidase inhibitor activity
Cellular component: extracellular exosome; extracellular region
Genetic constraint (gnomAD): Loss-of-function variants: 25 observed, 31.82 expected, observed/expected ratio (o/e) 0.79, 90% interval 0.57 to 1.1. The upper end of that interval is the gene's LOEUF score, 1.1, which puts it in group 4 of 6, group 1 being the genes least tolerant of losing a copy. Missense variants: 305 observed, 335.31 expected, observed/expected ratio (o/e) 0.91, 90% interval 0.83 to 1. Synonymous variants: 100 observed, 114.97 expected, observed/expected ratio (o/e) 0.87, 90% interval 0.74 to 1.03.
Homologues: Orthologues: chimpanzee SERPINI2 (99% identical), pig SERPINI2 (86% identical), rabbit SERPINI2 (85% identical), dog SERPINI2 (84% identical), rat Serpini2 (76% identical), mouse Serpini2 (76% identical). Paralogues in human: SERPINI1 (39% identical), SERPINB3 (35% identical), SERPINB6 (35% identical), SERPINB4 (34% identical), SERPINB12 (34% identical), SERPINC1 (32% identical), SERPINB10 (32% identical), SERPINB11 (32% identical), SERPINB1 (32% identical), SERPINB9 (32% identical), SERPINB8 (31% identical), SERPINB13 (30% identical), and 24 more.
Diseases named in the same sentence as SERPINI2 in open-access papers:
SERPINI2 is named in the same sentence as 7 diseases in open-access papers, as found by Europe PMC text mining. Sharing a sentence is not in itself a finding about the gene and the disease. The quoted sentences say what the papers report.
breast carcinoma (2 papers, 2020 to 2023). "The most upregulated genes, on the other hand, are less abundant (TPM < 100), such as SERPINI2, which encodes a protease inhibitor protein; CDH12, which, despite its role in cell adhesion and proliferation, is not commonly studied in breast cancer; and WDR, a gene about which little is known." (PMID 36982287, 2023).
diabetes (1 paper, 2024). "Prominent reduced proteins included secreted digestive enzymes; Reg2, a Reg family member that protects from diabetes; and Serpini2/Pancpin, a serpin family member crucial to maintaining acinar cell secretory function and identity." (PMID 38672675, 2024).
squamous cell lung carcinoma (1 paper, 2019). A carcinoma arising from squamous bronchial epithelial cells. "SERPINI2 is tumor suppressor gene and is associated with squamous cell lung cancer." (PMID 30704450, 2019).
tumor (3 papers, 2007 to 2021). "Some of them are considered as the tumor suppressor genes of PC, such as PLA2G1B, SERPINI2 and NR5A2." (PMID 31706267, 2019). "Moreover, as SERPINI1 and SERPINI2 were both reported to be down-regulated during tumor development, it is rational to doubt that the expression of PDCD10, which is located in between the two SERPINI genes at chromosome 3q26, may also be altered in some tumors." (PMID 17212813, 2007).
cancer (1 paper, 2023). A tumor composed of atypical neoplastic, often pleomorphic cells that invade other tissues. "Serpin family I member 2 (SERPINI2), a tumor suppressor gene downregulated in PDAC and other cancers, and microRNA mir-217 (MIR217), a potential tumor suppressor gene in PDAC, which targets KRAS expression, were among the most underexpressed genes in the OCM tumors." (PMID 36579622, 2023).
SERPINI2 also shares sentences with these, for which no sentence is quoted: infection (1 paper); metastasis (1).